TRIM37 (tripartite motif containing 37)
Diseases named in the same sentence as TRIM37 in open-access papers (continued):
Sharing a sentence is not in itself a finding about the gene and the disease.
genetic disorder (2 papers, 2018 to 2026). "In this review, we focus on the role of TRIM37 in the normal cell and in pathological conditions, with an emphasis on the MULIBREY (MUscle-LIver-BRain-Eye).genetic disorder caused by TRIM37 mutations." (PMID 30586926, 2018).
infection (1 paper, 2023). The state of being infected such as from the introduction of a foreign agent such as serum, vaccine, antigenic substance or organism. "Through a genetic burden test, we identified TRIM37 variants significantly associated with recurrent infection." (PMID 37528081, 2023). "Echoing with these records, our findings also suggested that TRIM37 is highly associated with an increased incidence of severe infection." (PMID 37528081, 2023). "To uncover the molecular mechanism of recurrent infection, we carried out whole-exome sequencing data of patients with recurrent infection and identified TRIM37 gene variants with a statistically significant association with recurrent infection." (PMID 37528081, 2023). "To explore whether TRIM37 is involved in regulating antibody production and recurrent infection, we constructed mice carrying the FINmajor mutation." (PMID 37528081, 2023). "Here, we revealed that TRIM37 variants were associated with recurrent infection." (PMID 37528081, 2023). "Therapeutic restoring the functionality of the TRIM37 mutant may provide a novel avenue to battle against recurrent infection and treat Mulibrey nanism." (PMID 37528081, 2023). "All this information indicated the importance of TRIM37 in protective immunity against infection." (PMID 37528081, 2023).
TRIM37 also shares sentences with these, for which no sentence is quoted: growth disorder (2 papers); 3M syndrome (1); adrenal hypoplasia (1); cardiovascular disorder (1); congenital heart disease (1); congestive heart failure (1); endometrial cancer (1); experimental autoimmune encephalomyelitis (1); familial Mediterranean fever (1); growth failure (1); heart disease (1); intracerebral hemorrhage (1); kidney tumors (1); lymph node metastasis (1); multiple sclerosis (1); non-alcoholic fatty liver disease (1); Obesity (1); peroxisomal disorders (1); Respiratory tract infection (1); schizophrenia (1); Silver-Russell syndrome (1); T-cell acute lymphocytic leukemia (1); triple-A syndrome (1); type 2 diabetes (1); Wilms tumor (1); X-linked Opitz/GBBB syndrome (1).